MT1XP1 (metallothionein 1X pseudogene 1)
Synonyms: formerly MTL1
Gene: Transcribed processed pseudogene on chromosome 1 (16,241,213 to 16,241,398, reverse strand). Ensembl gene ENSG00000233929.
Diseases named in the same sentence as MT1XP1 in open-access papers:
MT1XP1 is named in the same sentence as 1 disease in open-access papers, as found by Europe PMC text mining. Sharing a sentence is not in itself a finding about the gene and the disease.
MT1XP1 shares sentences with these, for which no sentence is quoted: bacterial infection (1 paper).